IKZF1 (IKAROS family zinc finger 1)
Diseases named in the same sentence as IKZF1 in open-access papers (continued):
Sharing a sentence is not in itself a finding about the gene and the disease.
multiple myeloma (continued). "Most important of these are IKZF1 and IKZF3, key MM survival transcription factors which sustain the expression of myeloma oncogenes IRF4 and MYC." (PMID 36439455, 2022). "Rev leads to the proteasomal degradation of IKZF1 and IKZF3, two transcription factors essential for myeloma cell proliferation, whereas this process should be inhibited by Vel." (PMID 34439244, 2021). "Recent studies showed that IMiDs bind to cereblon (CRBN), a substrate receptor of the CRL4–CRBN complex, to induce the ubiquitination and degradation of IKZF1 and IKZF3 in MM cells, contributing to their anti-myeloma activity." (PMID 34207079, 2021). "In multiple myeloma cells, CBIs raise the levels of the NK-activating ligands MICA and PVR through cereblon-dependent degradation of IKZF-1/3 and IRF4." (PMID 33411730, 2021). "In terms of mechanism, treatment with a pan-PIM kinase inhibitor promoted increased ubiquitination and subsequent degradation of IKZF1 and IKZF3, two transcription factors crucial for the survival of myeloma cells." (PMID 34503111, 2021). "Combining a pan-PIM kinase inhibitor with lenalidomide led to more effective degradation of IKZF1 and IKZF3 in multiple myeloma cells as well as xenografts of myeloma tumors." (PMID 34503111, 2021). "As critical transcription factors for lymphopoiesis and lymphoid malignancies, degradation of IKZF1 and IKZF3 by the CRL4CRBN E3 ubiquitin ligase complex mediates the anti-myeloma effect of lenalidomide." (PMID 34680233, 2021). "IMiDs bind to CRBN and recruit IKZF1 and IKZF3 for their ubiquitination and degradation, leading to the reduced proliferation of myeloma cells." (PMID 33392195, 2020). "In combination with CASP-8 inhibitor, Len further elevates the CRBN protein level, resulting in the enhanced degradation of IKZF1 and IKZF3 and enhanced anti-myeloma activity." (PMID 33392195, 2020). "Recent studies showed that IMiDs bind to CRBN, a substrate receptor of CRL4 E3 ligase, to induce the ubiquitination and degradation of IKZF1 and IKZF3 in multiple myeloma cells, contributing to their anti-myeloma activity." (PMID 31938543, 2020). "In 2014, two independent groups found lenalidomide-dependent CRL4CRBN substrates, Ikaros (IKZF1) and Aiolos (IKZF3), in multiple myeloma cell lines." (PMID 32414180, 2020). "The immunomodulatory imide drug (IMiD) lenalidomide promotes myeloma cell death via Cereblon (CRBN)-dependent ubiquitylation and proteasome-dependent degradation of IKZF1 and IKZF3." (PMID 30760870, 2019). "Downregulation of IKZF1/3 was demonstrated to induce downregulation of IRF4 and MYC5–7, two important proteins for myeloma proliferation and survival." (PMID 30741931, 2019). "IKZF1 and IKZF3 are transcription factors highly expressed in myeloma that contribute to myeloma cell survival." (PMID 30760870, 2019). "Ikaros family zinc finger protein 1 and 3 (IKZF1 and IKZF3) are transcription factors that promote multiple myeloma (MM) proliferation." (PMID 30760870, 2019). "This activation leads to the down-regulation of two transcription factors involved in B cell development (IKZF1 and IKZF3), highly expressed in multiple myeloma." (PMID 30190791, 2018). "The degradation of IKZF1 and IKZF3 induces cytotoxicity in myeloma cells because they are critical factors for B-cell differentiation." (PMID 28894755, 2017). "More recently it has been found that the CUL4-DDB1 complex can be modulated by binding of the drug, lenalidomide leading to degradation of lymphoid transcription factors IKZF1 and IKF3 in multiple myeloma cells." (PMID 26613412, 2015). "IKZF1 and IKZF3 zinc finger proteins are essential transcriptionfactors in multiple myeloma." (PMID 35856839, 2023). "Recently, PI and IMiD combination treatment was shown to work synergistically via calpain-dependent IKZF1 cleavage and stabilization of CRBN levels, suggesting that PI plus POM treatment might be a promising alternative for LEN-refractory myeloma." (PMID 38004369, 2023).
multiple myeloma (continued). "Nonetheless, bortezomib could potentiate the anti-myeloma effect of lenalidomide, suggesting that bortezomib may regulate the CRBN–lenalidomide–IKZF1/3 signaling pathway." (PMID 35321428, 2022). "This leads to ubiquitination and proteasomal degradation of the lymphoid transcription factors Ikaros (IKZF1) and Aiolos (IKZF3), which regulate expression of other genes such as IRF4 and MYC, and are essential for the proliferation and survival of multiple myeloma cells." (PMID 35197447, 2022). "Myeloma cells are addicted to several proteins like c-Myc, IRF4, and IKZF1." (PMID 35646666, 2022). "Therefore, the degradation of IKZF1 and IKZF3 decreases the expression of IRF4 and its downstream target MYC, resulting in growth inhibition of multiple myeloma cells." (PMID 34207079, 2021). "Reduced levels of IKZF1 and IKZF1 are observed in lenalidomide-sensitive but not -resistant myeloma cell lines." (PMID 34680233, 2021). "Transcription factors IKZF1 and IKZF3 are required for myeloma cells to undergo proliferation." (PMID 33392195, 2020). "IMiD-mediated degradation of IKZF1 and IKZF3 results in myeloma cell growth arrest as well as activation of T cells, both of which may contribute to anti-myeloma effects of IMiDs." (PMID 31231360, 2019). "CC-220 is a significantly more potent IKZF1 and IKZF3 degrader than IMiD drugs, and it is currently in clinical trials for relapsed/refractory multiple myeloma and systemic lupus erythematosus." (PMID 30234487, 2018). "Finally, lenalidomide was found to degrade both IKZF1 and IKZF3 in the context of multiple myeloma." (PMID 39029626, 2024). "Because the binding sequence of c‐FOS on the myeloma genome is different from common AP‐1‐binding motifs, such as TPA‐responsive elements and cAMP‐responsive elements, it is highly possible that c‐FOS binds to DNA through protein‐protein interactions with IKZF1." (PMID 37581569, 2023). "These molecules exert multiple direct and indirect anti-myeloma effects, primarily through binding to cereblon (CRBN), part of an E3 ubiquitin ligase complex, and promoting the ubiquitination of the IKAROS and AIOLOS family transcription factors (IKZF1 and IKZF3)." (PMID 37627065, 2023). "The fact that two of the identified RIDD targets, IRF4 and IKZF1, are targeted by IMiDs, made us hypothesize that the combination of these drugs with ER-stress inducers (that also lowered IRF4 and IKZF1 levels) could exert a synergistic anti-myeloma effect." (PMID 35361260, 2022). "This issue could be overcome by either hijacking two different E3 ligases, CRBN and VHL, or a PROTAC, such as YKL-06-102, that simultaneously targets IKZF1, IKZF3, and CDK6, achieving intramolecular synergistic effects even in IMiD-insensitive multiple myeloma cells." (PMID 35197447, 2022). "Furthermore, accumulating evidence demonstrated that downregulation of IKZF3 (Aiolos) and IKZF1 (Ikaros), two members of the IKZF family, in malignant plasma cells as well as in adaptative and innate lymphocytes is key for the anti-myeloma activity of Immunomodulatory drugs (IMiDs)." (PMID 36284352, 2022). "But based on the roles of IKZF1 and CRBN for eliciting anti-myeloma effects for any possible hematological response accompanying reduction in the disease burden (M-protein), it remains unclear if recovery of erythroid progenitors is CRBN or IKZF1 independent." (PMID 33014791, 2020). "Furthermore, under physiological conditions, IKZF1 and IKZF3 repress IL-2 gene expression in T cells but conversely stimulate expression of interferon-related factor 4 (IRF4) (a transcription factor essential for survival of myeloma cells)." (PMID 24687382, 2014). "Furthermore, although bortezomib blocks the degradation of IKZF1/3, ubiquitinated IKZF1/3 might not have transcriptional activity, and thus could mediate the anti-myeloma effect of lenalidomide." (PMID 35321428, 2022).
multiple myeloma (continued). "While translocation of the immunoglobulin loci is a common mode of oncogene overexpression in myeloma, the IgL locus is unique in that, regardless of IgL expression, the IgL enhancers appear to be very active and bound by some of the highest levels of IKZF1 in the myeloma epigenome." (PMID 31015454, 2019).
lymphoma (20 papers, 2014 to 2025). A malignant (clonal) proliferation of B- lymphocytes or T- lymphocytes which involves the lymph nodes, bone marrow and/or extranodal sites. "In particular, the tumor-suppressor gene Pten was frequently mutated in lymphomas induced by irradiation of infants, whereas the tumor-suppressor gene Ikzf1 was frequently mutated in lymphomas arising after irradiation of adults." (PMID 35336821, 2022). "In mouse models that IKZF1 null mice are prone to T-cell malignancies like T-ALL or lymphoma, nevertheless in the real world, humans harboring germline mutation of IKZF1 are more frequently linked to various types of immunodeficiency instead of malignancies." (PMID 38978740, 2024). "We found potential vulnerability to CK1α degradation in certain lymphoma cells refractory to IKZF1/3 degraders." (PMID 38265263, 2024). "Furthermore, even in wild-type mice, deletion of any one of the tumor suppressor genes Pax5, Sfpi1, Ikzf1, Pten or Cdkn2a has been reported specifically in irradiated animals in copy number analyses of lymphomas, acute myeloid leukemia and thymic lymphoma." (PMID 37117033, 2023). "Mice deficient for IKZF1 show a complete arrest in B-lymphocyte development while mice heterozygous for a dominant-negative mutation of IKZF1 develop T cell leukemia and lymphoma with a 100% penetrance." (PMID 26269779, 2015). "For instance, B-cell eCGIs are enriched for regions binding key TFs involved in B-lymphopoiesis and lymphoma pathogenesis (such as BCL11A, EBF1, IKZF1 and SPI1), whereas ESC-specific eCGIs are enriched for binding of NANOG, a key TF regulating pluripotency." (PMID 26512062, 2016). "Intriguingly, knock-down of IKZF1 sensitizes tumor cells in DLBCL to treatment with the EZH2 inhibitor tazemetostat, not only emphasizing its biological, but also a possible clinical impact in lymphoma." (PMID 37563306, 2023). "Multiple factors, such as EZH2, c-MYC, IKZF1, IKZF3, IRF4, and CDK6, which are essential for the proliferation and survival of malignant plasma cells and lymphoma, were decreased upon treatment with PM in all tested MM and lymphoma cell lines, including MM1S, MM1R, and TMD-8." (PMID 40562746, 2025).
acute myeloid leukemia (17 papers, 2013 to 2025). Acute myeloid leukemia (AML) is a group of neoplasms arising from precursor cells committed to the myeloid cell-line differentiation. "IKZF1 mutations are recurrent alterations in acute myeloid leukaemia (AML), and hotspot point mutation, N159S, has recently been associated with unique gene expression and adverse risk." (PMID 40041934, 2025). "Genetic mutations of IKZF1 have been frequently delineated in B‐lineage acute leukaemia (B‐ALL) but rarely elucidated in acute myeloid leukaemia (AML)." (PMID 37345307, 2023). "Only a few studies have reported the rare IKZF1 mutations in acute myeloid leukaemia with a low frequency." (PMID 37345307, 2023). "In acute myeloid leukemia, IKZF1 deletion has been demonstrated recurrent, but whether IKZF1 mutation also exists in AML remained largely unknown." (PMID 33081843, 2020). "It is also similar in terms of acute myeloid leukemia (AML), the frequency of IKZF1 somatic mutations is only 3.83%." (PMID 38978740, 2024). "In the last few years, much evidence supporting IKAROS involvement in myeloid differentiation has been reported, suggesting that loss of IKZF1 might also be a determinant of oncogenesis in acute myeloid leukemia." (PMID 36834692, 2023). "IKZF1 somatic alterations are also present in 1.2% of pediatric and 2.6-4.8% adult acute myeloid leukemia (AML) cases, underscoring its role in myeloid cancers." (PMID 40925926, 2025). "In adult acute myeloid leukaemia (AML), genomic IKZF1 alterations are reported in 2.6%–4.8% of patients, with a broader spectrum and distribution of variants." (PMID 40041934, 2025). "Of note, we have identified targets of transcription repressor IKZF1 in MDS cells and acute myeloid leukemia (AML) cells, including G protein-coupled receptor 68 (GPR68) and regulator of calcineurin 1 (RCAN1)." (PMID 34680233, 2021). "We have found that lenalidomide-mediated degradation of IKZF1 leads to activation of the G protein-coupled receptor 68 (GPR68)/calcium/calpain pro-apoptotic pathway and inhibition of the regulator of calcineurin 1 (RCAN1)/calcineurin pro-survival pathway in MDS and acute myeloid leukemia (AML)." (PMID 34680233, 2021). "We have identified signaling molecules downstream of IKZF1, G protein-coupled receptor 68 (GPR68) and regulator of calcineurin 1 (RCAN1) in myeloid malignancies, including MDS and acute myeloid leukemia (AML) with or without del(5q)." (PMID 34680233, 2021).
Immunodeficiency (17 papers, 2018 to 2026). Failure of the immune system to protect the body adequately from infection, due to the absence or insufficiency of some component process or substance. "Genetic testing demonstrated a heterozygous IKZF1 mutation, consistent with underlying immunodeficiency." (PMID 41878461, 2026). "IKZF1 mutations were associated with pancytopenia and immunodeficiency, while ETV6 mutations were linked to hypogammaglobulinemia." (PMID 40488176, 2025). "IKAROS family zinc finger 1 (IKZF1) is involved in lymphocyte development and pathogenic variants in IKZF1 are associated with immunodeficiency." (PMID 40971994, 2025). "It should be noted that recent findings have proposed a role for constitutional IKZF1 mutations in immunity, and have been related through immune deficiency with cases of T-ALL/LBL." (PMID 39272737, 2024). "Heterozygous germline variants in human IKZF1 encoding for IKAROS define an inborn error of immunity with immunodeficiency, immune dysregulation and risk of malignancy with a broad phenotypic spectrum." (PMID 38813543, 2024). "A myriad of different mutations in IKZF1 have been identified, spanning across the entire gene causing differential clinical outcomes in patients including immunodeficiency, immune dysregulation, and cancer." (PMID 34354970, 2021). "Inevitably, a negative screening result cannot absolutely exclude all combined immunodeficiencies, exemplified by the patient with the IKZF1 missense variant (PID_6) who presented after the newborn period." (PMID 32754152, 2020). "These mutations in IKZF1 impair the DNA binding of IKAROS to its target sequence and cause an immunodeficiency syndrome predominantly characterized by an antibody insufficiency." (PMID 31057532, 2019). "Additionally, a de novo heterozygous germline mutation in IKZF1 has been identified recently in 7 unrelated patients with an early-onset combined immunodeficiency." (PMID 31057532, 2019). "Consistent with this, mutations within SE regions of other genes, including GATA2, IKZF1, and IRF8, have similarly been implicated in distinct immunodeficiency syndromes by disrupting the development and function of DCs, NK cells, and additional immune subsets." (PMID 40895527, 2025). "Immunodeficiencies involve SE dysregulation affecting key TFs like BACH2, GATA2, and IKZF1, leading to impaired immune cell development and function." (PMID 40895527, 2025). "Mouse data and studies on patients with combined immunodeficiencies highlighted the role of the transcription factors TCF4 (also known as E2-2), IRF8 and Ikaros family zinc finger 1 (IKZF1) for pDC differentiation." (PMID 38504978, 2024).
autoimmune disease (16 papers, 2013 to 2025). "Building on the functional consequences of these 2 variants, we propose a disease model that is not only instructive for IgG4-RD but also for atopic diseases and autoimmune diseases associated with an IKZF1 risk haplotype." (PMID 38885295, 2024). "IKZF1 haplotypes have also been found to be associated with other autoimmune diseases, such as Crohn’s disease (rs1456896); ulcerative colitis (rs145689), multiple sclerosis (rs2018471), and type 1 diabetes mellitus (rs10272)." (PMID 38885295, 2024). "Though the evidence between IKZF1 and the risk of psoriasis is limited, several studies have demonstrated its relationship with autoimmune disease systemic lupus erythematosus (SLE)." (PMID 29715312, 2018). "Previous studies also found that IKZF1 is significantly associated with several autoimmune diseases, such as systemic lupus erythematosus (SLE), Crohn's disease and inflammatory bowel disease (IBD)." (PMID 28552951, 2017). "Finally, our functional insights into the GOF variant of IKAROS in mature T cell responses is relevant for the many autoimmune diseases associated with IKZF1." (PMID 38885295, 2024). "The IKZF1 (IKAROS family zinc finger 1 (Ikaros)) gene is located at 7p12.2, encodes a transcription factor related to chromatin remodeling, regulates lymphocyte differentiation, and has been reported to be associated with some autoimmune diseases." (PMID 28552951, 2017). "Our results highlighted the critical role of EBV infection as a trigger for both autoimmune disorders and B-ALL: tissue-specific analysis revealed enriched risk loci in EBV-transformed lymphocytes, and the central role of IKZF1 in this cell was also identified by gene-level analyses." (PMID 38616254, 2024). "The constructed gene networks revealed among the exome genes, partners previously implicated in autoimmune diseases, including the SLE-associated genes IKZF1, IKZF3, and ITGAX25,50,51, further supporting a role for the genes identified in the disease pathogenic pathways." (PMID 29884787, 2018). "Data presented in this report support that Ikzf1 hyperlactylation inhibits IL-2 expression and then promotes TH17 differentiation, providing mechanistic explanation for posttranslational modification–regulated IL-2 expression in autoimmune diseases." (PMID 37851814, 2023).